INS (insulin)
Diseases named in the same sentence as INS in open-access papers (continued):
Sharing a sentence is not in itself a finding about the gene and the disease.
COVID-19 (continued). "This distinction might have clinical relevance as it would determine whether to prioritize the normalization of blood glucose vs. insulin levels, in order to reduce ACE2 expression and ultimately COVID-19 severity." (PMID 32574288, 2020). "We present two cases of patients with DKA and COVID-19 treated with an insulin regimen with no further complications." (PMID 32953287, 2020). "Therefore, metformin and AGIs might be more suitable for patients with COVID-19 and T2DM while insulin might be used with caution." (PMID 38755442, 2024). "COVID-19-specific mechanisms such as increased levels of IFN-γ and reduction of ACE2 levels following SARS-CoV-2 infection could contribute to insulin resistance in skeletal muscle, although specific evidence is lacking." (PMID 37934800, 2024). "In patients with COVID-19 and T2DM, metformin or AGIs might be prioritized over insulin." (PMID 38755442, 2024). "Moreover, insulin infusion, but not anti-hyperglycemic drugs, is the only option for COVID-19 patients with critically ill hyperglycemia." (PMID 36839456, 2023). "While the need for insulin is normally limited in women with GDM, it should be kept in mind that the need for insulin increases with a history of COVID-19, and dysglycemia treatment in GDM patients with a history of COVID-19 may require enhanced care in terms of blood glucose regulation." (PMID 37927616, 2023). "Although there has been no glucose disturbance ongoing in recovered COVID-19 patients, whether the organ regulation function of insulin resistance returned to normal remains unknown." (PMID 37789017, 2023). "However, 75% of subjects of the COVID-19 cohort with virus-negative pancreatic tissues were treated with glucocorticoids, which are known to antagonize insulin signaling and production." (PMID 37246981, 2023). "Similarly, Eli Lilly promoted the development of biologics to treat COVID-19 and secured non-prescription availability of Insulin." (PMID 36530653, 2022). "The ability of LL-37 to encourage insulin release and its role in the proper function of NETs in diabetic and hyperglycemic patients could provide another tool in the fight against SARS-CoV-2, since it addresses a major comorbidity of severe COVID-19." (PMID 35634307, 2022). "In the nonsevere and severe disease groups, favorable outcomes were more prevalent among COVID-19 patients receiving oral medication only or oral medication plus insulin than among the insulin-only group (100%, 100% vs. 60% for nonsevere, p=0.020; 97.4%, 100% vs. 73.3% for severe, p=0.034)." (PMID 35047039, 2022). "We did not have previous data on insulin sensitivity in our group of COVID-19 patients, and this may have misled us into including diabetic patients who were not known with the diagnosis." (PMID 36312630, 2022). "However, the use of glibenclamide in DM patients with COVID-19 has not been evaluated since most DM patients with COVID-19 are switched to insulin therapy." (PMID 34124187, 2021). "In general, insulin use did not affect the hospitalization time of COVID-19 patients." (PMID 34367067, 2021). "Indeed, COVID-19 may have a dynamic impact on the long-term complications regarding the development of T2DM and/or progression of orally controlled T2DM to an insulin-dependent type of T2DM." (PMID 33202960, 2020). "This gives credence to the hypothesis of inherent insulin resistance within the patients affected by COVID-19, regardless of illness severity." (PMID 33198177, 2020). "Furthermore, among the many signaling pathways, the Insulin pathway showed a significant negative enrichment in both COVID-19 and IPF groups, the physiological significance of which needs to be further verified." (PMID 33264345, 2020). "Intensive insulin therapy has significant anti-inflammatory effects during critical illness; hence, it should not be discontinued in patients with DM who develop COVID-19 and should be considered for patients receiving oral antidiabetic drugs who have a poor glycemic profile." (PMID 33297431, 2020).
COVID-19 (continued). "However, given the current circumstances where there is no accumulated evidence to support the use of other agents, insulin appears to be the best choice for diabetic inpatients with COVID-19." (PMID 33195481, 2020). "Patients who are overweight, obese, or have metabolic disorders tend to have different serum levels of adipokines and EB (cortisol, C-peptide, GLP-1, insulin, and PYY) compared to those without metabolic comorbidities, which could be associated with poor outcomes in patients with COVID-19." (PMID 39109758, 2024). "Although metformin and insulin may not, per se, act as universal indicators of death in diabetic patients with COVID-19, their role could vary within the higher personalization of the risk assessment model (through adding and exploring their interactions with various patient characteristics)." (PMID 38540218, 2024). "The primary outcome of total intravenous regular human insulin infusion requirements needed during the diabetic ketoacidosis episode was not statistically significant and resulted in 1.79±0.61 units/kg/day in the COVID-19 positive group and 1.81±0.6 units/kg/day in the negative group (p=1)." (PMID 36741601, 2023). "Glucose levels >88 mg/dL (AUC 0.781, Sn 74%, Sp 75%, PPV 61%, NPV 84%) and insulin levels >11.5 mUI/mL (AUC 0.994, Sn 95%, Sp 94%, PPV 90%, NPV 97%) were the cut-off points that were associated with the development of IR in non-diabetic patients without COVID-19 history." (PMID 36312630, 2022). "Furthermore, cells staining negative for insulin but positive for β-cell lineage markers have been observed in biopsy specimens from deceased COVID-19 patients, suggesting that SARS-CoV-2 infection might hinder hormone expression in β cells." (PMID 35053020, 2021). "After six months of infection, patients who developed severe COVID-19 presented reduced GH and IGF-1, as compared with controls, whereas the insulin levels were not different." (PMID 40709999, 2025). "As in nondiabetic patients with mild COVID-19 symptoms, there was no significant alteration in serum FGF7 and insulin levels compared to the control." (PMID 38654010, 2024). "The mean total daily insulin dose was 54 ± 26 U, and the mean total bolus insulin dose was 21 ± 10 U. During the study period, there were no SARS-CoV-2 infections or overt COVID-19 cases among study participants." (PMID 36014822, 2022). "Second, the lack of detection results of glycosylated hemoglobin A1C, insulin level, TNF-α, IFN, IL-1β, and other cytokines limited the deeper assessment of glycemia and immune dysfunction in COVID-19 patients with T2DM." (PMID 37359706, 2022). "Thus, insulin may not be a suitable marker for the detection of β cells in patients with COVID-19." (PMID 35053020, 2021). "Our study identifies COVID-19 ICU patients spent significantly less TIR (70–150 mg/dL) and utilized higher average daily insulin as compared to non-COVID-19 ICU patients." (PMID 33198177, 2020). "This suggests that insulin management may not need to be more aggressive when managing a patient with both DKA and COVID-19, but rather that these patients are likely to require IV RHI infusion for a prolonged time." (PMID 36741601, 2023). "In that study, the COVID-19-related mortality in T2DM was significantly lower in patients prescribed metformin, SGLT2 inhibitors, and SU and higher in patients prescribed DPP-4 inhibitors and insulin vs. those not prescribed these medications." (PMID 36017317, 2022). "An encouragement to chase this track more in depth comes from the observation that in non-COVID-19 critically ill hyperglycemic patients admitted at ICU, plasma levels of sRAGE are higher in DM vs. non-DM patients, and reduced by intensive insulin therapy only in DM patients." (PMID 32760352, 2020).
COVID-19 (continued). "Targeted interventions, including simplification of the insulin regimen from CSII to MDI and zinc repletion, proved effective in stabilizing glycemic control and restoring patient confidence, although one further hospitalization occurred due to post-COVID-19 anorexia without DKA." (PMID 41179041, 2025). "The favorable prognosis of patients with moderate COVID-19 and T2DM, especially for those without severe diabetic complications in our study, may partly be due to the use of glucose-lowering medicine such as metformin and/or insulin." (PMID 33490288, 2021). "Both insulin and GLP-1RAs have shown optimal glucose-lowering and anti-inflammatory effects in type 2 diabetic patients and may represent a valid therapeutic option to treat asymptomatic and non-critically ill COVID-19 diabetic patients." (PMID 32698837, 2020).
Anxiety (364 papers, 2007 to 2026). Intense feelings of nervousness, tension, or panic often arise in response to interpersonal stresses. "Insulin signaling in the brain is closely linked to dopaminergic function: central insulin resistance impairs dopamine turnover, leading to decreased reward processing, increased anxiety, and depressive-like behaviors in both rodents and humans." (PMID 40869170, 2025). "Insulin, glucocorticoids, mineralocorticoids, and type 3 serotonin receptor antagonists were also effective in alleviating anxiety-like behavior associated with STZ-induced T1D in mice." (PMID 38279738, 2024). "Since injections under the skin have been linked to pain, discomfort, and anxiety, pens for administering insulin, with shorter needles, have been chosen as an alternative to vials and syringes, because they can cause less pain and reduce skin harm." (PMID 37836872, 2023). "At ∼36 weeks gestation, 27% of women with GDM treated with insulin had scores associated with an increased risk of anxiety (STAI-6 ≥ 15)." (PMID 36733299, 2023). "It has been shown that different dietary fat types cause specific alterations in anxiety- and depressive-like behavior as well as in insulin sensitivity." (PMID 37881580, 2023). "Preoperative carbohydrate drinks have been associated with reduced anxiety, postoperative nausea and vomiting, postoperative insulin resistance, and length of hospitalization." (PMID 36310325, 2023). "While the WJMSC-CM and insulin-treated diabetic groups were associated with a reduction in anxiety-like behaviors as evidenced by an increase in time spent in the central part and total distance traveled when compared with the untreated diabetic group." (PMID 37081849, 2023). "As IN-insulin reverses anxiety-like behavior in rodents, and rats deficient in brain insulin receptors exhibit anxiety and depressive-like behavior, IN-insulin has been explored in a few clinical trials for its ability to modulate anxiety and fear." (PMID 36429060, 2022). "Although prolonged fasting causes adverse effects like dehydration, hunger, anxiety, nausea and insulin resistance, quality-improvement projects aiming to reduce actual fasting times in adults are rare." (PMID 34702191, 2021). "A recent study demonstrated that astrocytes are a direct insulin target in the brain and that knockout of IR on astrocytes causes increased anxiety- and depressive-like behaviors in mice." (PMID 33547374, 2021). "Secondly, ERAS protocols reduce fasting time and increase carbohydrate intake to relieve the stress of hunger and anxiety before CS, decreasing the insulin resistance and the loss of nutrition in the postoperative period." (PMID 34409050, 2021). "Studies have revealed that anxiety and fear of injection-associated pain have been reported to affect approximately 30–50% of patients initiating insulin." (PMID 34616293, 2021). "Hypodermic injections are a cause for great anxiety and reduced adherence to the subcutaneous application of insulin for glycemic control in diabetics or in the treatment of multiple sclerosis, increasing the risk of complications and mortality." (PMID 33029335, 2020). "Here, we complement our previous metabolic findings on TauKO mouse by investigating the impact of tau loss of function on systemic insulin sensitivity, anxiety-related behavior and memory." (PMID 32226410, 2020). "Although some participants reported anxiety and side effects associated with metformin and insulin, these were outweighed by the perceived benefits for their health and that of the unborn baby." (PMID 31765431, 2019). "Previously, we found that elevated levels of anxiety symptoms were associated with a later initiation of insulin, which appeared to be partly explained by better glycemic control in the anxious group, while elevated depressive symptoms were not." (PMID 27537359, 2016).
Anxiety (continued). "Administration of insulin through oral route causes the avoidance of pain during the injection (in subcutaneous administration), anxiety due to needle, and infections which can be developed." (PMID 26556194, 2014). "Oral insulin will cause the avoidance of pain during the injection (in subcutaneous administration), anxiety due to needle, and infections which can be developed." (PMID 26556194, 2014). "There is evidence that hormones associated with energy status of the mother such as insulin and leptin as well as expression of neurotransmitters associated with reward such as dopamine can impact on anxiety and other behaviour disorders of offspring." (PMID 24027581, 2013). "SERT deficiency has been associated with anxiety and glucocorticoids play an important role in insulin sensitivity." (PMID 22412882, 2012). "Insulin concentrations predicted anxious-depressed symptoms, social difficulties, and hyperactivity, whereas HbA1C was associated with social, attention, anxiety, depressive and affective problems, hyperactivity, and broader internalizing and total problem difficulties." (PMID 41515266, 2026). "Multivariate analysis showed that having Severe Non-Proliferative Diabetic Retinopathy or having Proliferative Diabetic Retinopathy and receiving insulin as therapy (alone or in combination with another treatment), was significantly associated with greater anxiety symptoms." (PMID 37998065, 2023). "Also, being treated with insulin (alone or in combined treatment) was significantly associated with greater anxiety." (PMID 37998065, 2023). "Also, being treated with insulin as a monotherapy or in combination was significantly associated with greater anxiety symptoms." (PMID 37998065, 2023). "Multivariate analysis showed that having Severe Non-Proliferative Diabetic Retinopathy or having Proliferative Diabetic Retinopathy and receiving insulin therapy (alone or in combination with another treatment), were significantly associated with higher levels of anxiety." (PMID 37998065, 2023). "While there is currently a few research looking at the association between anxiety and IO, higher levels of HbA1c have been found in people with T1D and comorbid anxiety, which could indicate engagement in insulin omitting behaviours." (PMID 34121470, 2021). "It has been found that the pain and anxiety associated with daily insulin injections may increase the risk of insulin omission in diabetic patients." (PMID 32455131, 2020). "Results suggest that the co-administration of Cd and Hg to female mice during the early development of their offspring (the periconception period) was associated with anxiety-like behavior, altered glucose metabolism, and insulin resistance in male offspring at adulthood." (PMID 27814245, 2017). "The initiation of insulin therapy, that occurred in 31.5% of Italian and 40% of immigrant women, increased women's anxiety because they believed that insulin might cause problems for their unborn child." (PMID 22611394, 2012). "Hence, altered insulin signaling in the amygdala prior to or following acute stress exposure may predispose an individual to persistent anxiety-like behavior." (PMID 40978196, 2025). "Similarly, exploiting the underlying mechanisms involved in insulin actions on striatal astrocytes in anxiety, i.e., by regulating ATP release, activation of PY2 receptors and dopamine transmission, could be explored as well." (PMID 36979453, 2023). "The Western group exhibited increased caloric intake, body fat, insulin resistance, and sympathetic nervous system and hypothalamic–pituitary–adrenal activity relative to the Mediterranean group —all of which have been associated with either social isolation or anxiety or both." (PMID 35889809, 2022).